CTLA4 (cytotoxic T-lymphocyte associated protein 4)
Diseases named in the same sentence as CTLA4 in open-access papers (continued):
Sharing a sentence is not in itself a finding about the gene and the disease.
hypophysitis (continued). "In CTLA-4 inhibitor-induced hypophysitis, a type II hypersensitivity reaction, followed by a type IV hypersensitivity reaction, has been implicated." (PMID 39941803, 2025). "A prospective study showed that CTLA-4 inhibitors caused IAD and hypophysitis, while PD-1 or PD-L1 inhibitors only caused IAD." (PMID 40919154, 2025). "Previous studies indicated that irH induced by anti-CTLA-4 implicates a type II hypersensitivity reaction with the activation of the classical complement pathway and secondary development of hypophysitis." (PMID 41020004, 2025). "A Japanese study showed that HLACw12 and HLA-DR15 were significantly associated with anti-CTLA4-related hypophysitis, whereas HLA-DQB106:01, HLA-DPB109:01, and HLA-DRB5*01:02 were significantly associated with anti-PD-1-related hypophysitis." (PMID 41465179, 2025). "Hypophysitis is the second most common endocrinopathy associated with ICI treatment affecting approximately 6%, especially when CTLA-4 inhibitors are used alone or in combination with PD-1 antagonists." (PMID 41140515, 2025). "CTLA-4 inhibitor-mediated hypophysitis likely involves a type II hypersensitivity reaction, followed by a type IV hypersensitivity reaction." (PMID 41002414, 2025). "Hypophysitis, an inflammation of the pituitary gland, is a rare complication of immune checkpoint inhibitor (ICI) therapy, primarily associated with anti-CTLA-4 based treatments." (PMID 39859105, 2025). "The timing of onset of hypophysitis is earliest with combination therapy with median 1–3 months, followed with anti-CTLA-4 monotherapy (median 9–11 weeks), and usually later with anti-PD-1/PD-L1 monotherapy with median 4–7 months." (PMID 41373773, 2025). "Thyroid dysfunction occurs in up to 20% of patients receiving PD-1 or programmed death-ligand 1 (PD-L1) inhibitors, while hypophysitis is more commonly seen with CTLA-4 inhibitors, affecting approximately 10% of treated individuals." (PMID 40932982, 2025). "Gastrointestinal inflammation and hypophysitis are more common with CTLA‐4 blockade, while thyroiditis, pneumonitis, and autoimmune diabetes are more commonly associated with PD‐1 blockade." (PMID 40620216, 2025). "In regard to hypophysitis as described in adults, it has been found to occur more commonly with anti-CTLA-4 agents (ranging from 3.0–10.0 %) and combination therapy (approximately 7.0 %), but no pediatric cases have been reported thus far." (PMID 39680426, 2025). "The risk of developing hypophysitis is strongly correlated with the specific class of ICI used, with the highest incidence with combined anti-CTLA-4 and anti-PD-1/PD-L1 agents, with rates from 6.4% to 19%." (PMID 41373773, 2025). "Although hypophysitis is reported in 5.6% of patients receiving anti-CTLA4 antibodies and in 0.5%–1.1% of patients receiving anti-PD1 antibodies, hypogonadism is rarely described." (PMID 40230698, 2025). "Hypophysitis induced by CTLA-4 inhibitors, particularly ipilimumab and CTLA-4-based combination therapies, is more commonly associated with hypopituitarism than that caused by other ICPi classes." (PMID 41510421, 2025). "Anti–CTLA-4 antibodies mobilize naïve T cells, inducing lymphocytic infiltration of the pituitary gland and leading to hypophysitis and secondary adrenal insufficiency." (PMID 41301042, 2025). "The overall incidence of hypophysitis is 12% in patients treated with anti-CTLA-4 antibodies and 0.5% in patients treated with PD-1 antibodies." (PMID 39451777, 2024). "For instance, hypophysitis is more prevalent following treatment with anti-CTLA-4 drugs like ipilimumab, while thyroid dysfunction is more commonly associated with anti-PD-1 drugs such as nivolumab and pembrolizumab." (PMID 38169638, 2024). "Administration of an anti-CTLA-4 antibody results in both isolate ACTH deficiency and hypophysitis, while treatment with an anti-PD-1 or PD-L1 antibody only induces isolate ACTH deficiency." (PMID 39021640, 2024).
hypophysitis (continued). "One of the most prominent cases is ICI-mediated hypophysitis, which is triggered by ipilimumab, as a consequence of the strong expression of CTLA4 in the anterior pituitary gland." (PMID 38611115, 2024). "MRI abnormalities (signs of hypophysitis or empty sella syndrome) were only seen in patients treated with anti-CTLA-4 mono- or combination therapy." (PMID 39135626, 2024). "Tremelimumab, an IgG2 anti-CTLA-4 antibody, has shown a lower incidence of hypophysitis due to reduced complement activation potential." (PMID 39682118, 2024). "The same authors found a higher prevalence of hyponatremia in anti-PD-(L1) versus anti-CTLA-4 induced hypophysitis (62% versus 39%, respectively)." (PMID 39135626, 2024). "Anti-CTLA-4-induced hypophysitis typically shows MRI abnormalities (98%), characterized by enlargement of the pituitary gland and multiple anterior pituitary hormone deficiencies." (PMID 38910605, 2024). "In normal healthy pituitary cells, CTLA4 is expressed widely, leading to hypophysitis as a common immune-related adverse event in anti-CTLA4 treatment." (PMID 39000121, 2024). "The major cause of hypopituitarism is hypophysitis, whose incidence increases to 6.4% with the use of anti-PD-1/CTLA-4 antibody combination, compared to 3.2% with anti-CTLA-4 antibodies alone, and 0.4% with anti-PD-1 antibodies." (PMID 38910605, 2024). "Patients with monotherapy anti-CTLA-4 induced hypophysitis were more frequently treated with HD corticosteroids." (PMID 39135626, 2024). "Pituitary abnormalities on MRI (hypophysitis or secondary empty sella syndrome) were only seen in patients receiving anti-CTLA-4 or anti-CTLA-4/PD-1 therapy." (PMID 39135626, 2024). "Headache was mainly present in patients with anti-CTLA-4 and anti-CTLA-4/PD-1 induced hypophysitis (83% and 58% of patients, respectively versus 8% of patients with anti-PD-(L)-1 induced hypophysitis)." (PMID 39135626, 2024). "One study reported that among 273 patients with malignant melanoma and prostate cancer treated with ipilimumab, a monoclonal antibody directed against cytotoxic T-lymphocyte antigen-4 (CTLA-4), 9 (3.3%) were diagnosed with hypophysitis." (PMID 39356415, 2024). "Although the observed incidence of hypophysitis was 3.2% in anti-CTLA-4 antibody, 0.4% in anti-PD-1 antibody, and less than 0.1% in anti-PD-L1 antibody, the incidence was increased to 6.4% in the combination therapy group." (PMID 38318292, 2024). "Headache is present in 80–85% of patients with CTLA4 hypophysitis, and the majority display pituitary and multiple hormonal deficiencies." (PMID 36982990, 2023). "MRI abnormalities are seen in 81% of cases treated with anti-CTLA-4, whereas in 18% of patients with hypophysitis treated with anti-PD-1/anti-PD-L1, the initial enlargement of the pituitary returns to normal within weeks." (PMID 36983597, 2023). "Hypophysitis exhibits a higher incidence rate among patients undergoing anti-CTLA-4 therapy, with the potential to affect approximately 10% of the patient’s population." (PMID 37779728, 2023). "The observed incidence of hypophysitis varies from 1.8 to 5.6% for CTLA-4 blockade and from 7.7 to 10.5% for combination therapy, while in the case of PD-1 inhibitors, it ranges from 0.3 to 1.1% and <0.1%." (PMID 38136332, 2023). "Although the MRI often shows a mild to moderate swelling of the hypophysitis in the context of a CTLA-4 induced hypophysitis, the MRI is more valuable in the exclusion of a differential diagnosis (metastasis, primary hypophysitis)." (PMID 37271776, 2023). "The frequency of hypophysitis is higher in patients treated with monoclonal antibodies against CTLA-4 (1–18%) than those treated with PD-1 inhibitors (0.5–1.5%)." (PMID 37568563, 2023). "Results showed that individuals receiving combination therapy with anti-CTLA-4 and anti-PD- had a higher incidence of thyroid dysfunction and hypophysitis when compared to patients on CTLA-4 inhibitors or PD-1 inhibitors alone." (PMID 37251665, 2023).
hypophysitis (continued). "Hypophysitis is the most common irAE in patients treated with anti-CTLA-4 antibodies (approximately 5% of patients) and is more common in patients treated with the combination of ipilimumab and nivolumab, although the mechanism is not fully understood." (PMID 37304306, 2023). "As for women, it is known that ICIs can cause hypophysitis, with the highest incidences for the combination of anti-PD1 and anti-CTLA4." (PMID 37240854, 2023). "In contrast to anti-CTLA4 monoclonal antibodies, hypophysitis from anti-PD1 monoclonal antibodies appears after 6 months." (PMID 36982990, 2023). "The first reported case of immune checkpoint inhibitor (ICI)-induced hypophysitis is from the National Cancer Institute in 2003, in a patient with metastatic melanoma managed with ipilimumab, the monoclonal antibody for CTLA4." (PMID 36982990, 2023). "Autoimmune-based hypophysitis can occur in patients treated with anti-CTLA4 drugs alone (mean incidence 13%) or in combination with anti-PD1 drugs and, less frequently, with anti-PD1 or anti-PDL1 drugs alone." (PMID 37623012, 2023). "The authors demonstrated that the CTLA-4 antigen was expressed in all pituitary endocrine cells but that the highest level was found in the patient with severe hypophysitis." (PMID 37568563, 2023). "Although APAs are negative at baseline, one study demonstrated that APAs became positive at the onset of ipilimumab (anti-CTLA-4 antibody)-induced hypophysitis in all examined patients." (PMID 37623461, 2023). "The rate of hypophysitis is 5.6% for ipilimumab (CTLA4-inhibitor), 0.5% for nivolumab (PD1-inhibitor), 1.1% for pembrolizumab (PD1-inhibitor) and 8.8–10% for the combination." (PMID 37240854, 2023). "Hypophysitis is one of the most common endocrine irAEs and occurs mainly in patients treated with CTLA-4 inhibitors or combined ICI regimens." (PMID 38136332, 2023). "The pathogenesis of anti-CTLA-4 antibody-induced hypophysitis is a result of type II and IV hypersensitivity and the humoral immune response." (PMID 36982990, 2023). "A meta-analysis from 2018 reported hypophysitis more often as endocrine irAE related to anti-CTLA-4 antibodies and a low incidence of 0.4% of patients treated with anti-PD-1 antibodies." (PMID 37238273, 2023). "Immune checkpoint inhibitors induce hypophysitis (IIHs): IIHs is an increasingly frequent toxicity of in patients on treatment with inhibitors targeting cytotoxic T-lymphocyte antigen 4 (CTLA-4) and programmed cell death-1 (PD-1)." (PMID 37623461, 2023). "Headache is more frequent in patients treated with CTLA-4-inhibitor or combination therapy, while the predominant symptoms of PD-1/PD-L1-inhibitor induced hypophysitis are fatigue, anorexia and myalgias." (PMID 35912205, 2022). "Hypophysitis incidence is 3.2% for anti-CTLA4 mAbs, 0.4% for anti-PD-1 mAbs, and <0.1% for anti-PD-L1 mAbs, when used as a single agent, and 6.4% for combination therapy." (PMID 35205804, 2022). "Pituitary gland enlargement on MRI was almost universal in one multi-center review for patients with hypophysitis following CTLA-4 therapy, while this was only seen in a minority of cases (28%) resulting from anti-PD-1 therapy." (PMID 35912205, 2022). "In the first murine model of anti-CTLA-4-related (anterior) hypophysitis, obtained by repeated administrations of an anti-CTLA4 mAb, pituitary infiltration with hematopoietic mononuclear cells (mainly CD45+ lymphocytes) was demonstrated." (PMID 35311088, 2022). "The disproportionate higher incidence of hypophysitis with CTLA-4 inhibitors is best explained by the presence of CTLA-4 granules in normal pituitary glands of some individuals." (PMID 35967881, 2022). "While colitis, hypophysitis, and rash were common with anti-CTLA-4 ICIs, pneumonitis, hypothyroidism, arthralgias, and vitiligo were common with anti-PD-1 therapy." (PMID 35453540, 2022).
hypophysitis (continued). "Overall, the observed incidence of hypophysitis was 6.4% for combination therapy, 3.2% for CTLA-4 inhibitors, 0.4% for PD-1 inhibitors, and less than 0.1% for PD-L1 inhibitors." (PMID 35453540, 2022). "Among patients with hypophysitis, isolated adrenocorticotrophic hormone deficiency (IAD) is the main presentation, as well as headache (particularly with anti-CTLA4)." (PMID 36482425, 2022). "Most patients treated with an anti-CTLA-4 develop hypophysitis within several weeks after treatment initiation (mean time to onset 10.5 ± 4.8 weeks)." (PMID 36149449, 2022). "A human autopsy series showed disproportionately high CTLA-4 antigen expression within the pituitary of patients who had developed ICI-induced hypophysitis." (PMID 35912205, 2022). "Whereas ICI-induced hypophysitis and colitis are more common following CTLA-4 compared with PD-1 inhibition (2.3-18% versus 1.2-2.2% and 29-45% versus 3.9-25% respectively)." (PMID 35912205, 2022). "MRI abnormalities are seen in 81% of cases due to anti-CTLA-4 treatment and in 18% of patients with a hypophysitis who were treated with anti-PD-1/anti-PD-L1, typically with an initial enlargement of the pituitary, which returns to normal within weeks." (PMID 36149449, 2022). "For example, severe hypophysitis is reported in up to 5% of patients treated with ipilimumab but is extremely rare (<1%) in genetic CTLA4 haploinsufficiency." (PMID 35912205, 2022). "Colitis, hypophysitis, and rash are more common with CTLA-4 inhibitors, whereas pneumonitis, hypothyroidism, arthralgia, and vitiligo are more common with anti-PD-1." (PMID 35919497, 2022). "They found that CTLA-4 expression was highest in severe hypophysitis patients compared to other pituitary glands." (PMID 36713389, 2022). "In cases of immunotherapy-induced hypophysitis (IIH), an autopsy study showed that anterior pituitary cells express CTLA-4, causing T-cell infiltration, IgG-dependent complement fixation, and phagocytosis under CTLA-4 blockade." (PMID 34518996, 2022). "There are no other specific risk factors, but some authors have reported higher incidence of hypophysitis in male patients of older age, with a possible explanation lying in the positive effect of androgens, on CTLA-4 expression." (PMID 36612243, 2022). "Contrary to hypophysitis, the incidence of thyroiditis is higher with PD-1/PD-L1 inhibitors and lower with CTLA-4 inhibitors." (PMID 35967881, 2022). "As the incidence of ICI-induced hypophysitis is higher with anti-CTLA4-mAbs than anti-PD1/PD1L mAbs most data on the pathogenesis of ICI-induced pituitary damage derive from studies on anti-CTLA4-mAbs." (PMID 35311088, 2022). "Out of 276 patients with hypophysitis described in the literature between 2003 and 2019, 70% were secondary to CTLA-4 blockade, 23% to PD-1 blockade, 2% to PD-L1 blockade, and 3.9% to combination therapy (CTLA-4 and PD-1)." (PMID 36149449, 2022). "They showed that higher levels of CTLA-4 in the pituitary can result in hypophysitis through T cell and antibody dependent immune mechanisms, during CTLA-4 blockade." (PMID 36713389, 2022). "CTLA-4 induced hypophysitis usually presents within weeks of ICI commencement (mean 9 weeks), whereas anti-PD-1-induced disease is more variable, but tends to occur later (mean 26 weeks)." (PMID 35912205, 2022). "Involvement of the posterior pituitary with central diabetes insipidus (DI) is overall rare, only described in 3% of anti-PD-1- and anti-CTLA-4-induced hypophysitis." (PMID 36149449, 2022). "A patient who received anti-CTLA-4 Abs with evidence of severe hypophysitis, both clinical and histological, showed high levels of pituitary CTLA-4 expression, T-cell infiltration, and immunoglobulin G (IgG)-dependent complement fixation and phagocytosis." (PMID 35237154, 2022).
hypophysitis (continued). "Compared to PD-1 monotherapy, hypophysitis more commonly occur during ipilimumab (an anti-CTLA4 mAb) monotherapy (OR, 0.29; 95% CI, 0.18–0.49; p < 0.001) than in combination therapy (OR, 2.2; 95% CI, 1.39–3.60; p = 0.001)." (PMID 35205804, 2022). "A clinical study of CTLA-4 antibody in melanoma patients with hypophysitis suggested better antitumor efficacy was achieved." (PMID 34094910, 2021). "Hypophysitis is an irAE that appears to be more common with anti-CTLA-4 agents than PD-1/PD-L1 inhibitors, with rates of hypophysitis up to 11% among individuals receiving ipilimumab." (PMID 34868071, 2021). "For example, CTLA-4 is highly expressed on the pituitary gland, and hypophysitis is frequently seen in patients treated with an anti–CTLA-4 but not with an anti–PD-1 antibody." (PMID 35126126, 2021). "Hypophysitis secondary to anti-PD-1/PD-L1 therapy is considered extremely rare and more frequently observed secondary to anti-CTLA-4 therapy." (PMID 34660286, 2021). "Remarkably, hypophysitis is considerably more prevalent in patients treated with anti-CTLA4 antibodies than in patients with CTLA4 haploinsufficiency." (PMID 35154081, 2021). "In particular, among these, an immune-targeted cancer therapy-related hypophysitis has been recognized as an endocrine irAE with a higher prevalence in patients treated with anti-CTLA-4 with respect to those treated with anti-PD and anti-PD-L1 agents." (PMID 34439190, 2021). "The rate of hypophysitis is 5.6% for anti-CTLA4, 0.5%-1.1% for anti-PD1, and 8.8-10% for the combination." (PMID 34597942, 2021). "It has been reported that the ectopic expression of CTLA-4 on the pituitary gland contributes to ICI-induced hypophysitis." (PMID 34732257, 2021). "In CTLA-4 inhibitor-related hypophysitis, it has been reported that the CTLA-4 expression in the anterior pituitary cells evoked a direct interaction of anti-CTLA-4 antibody with these cells and induced a complement-dependent cell injury in the pituitary." (PMID 33977343, 2021). "For example, hypophysitis is thought to result from complement activation by C1q binding to the Fc fragment of anti-CTLA4 antibody." (PMID 35154081, 2021). "Hypophysitis represents the most frequent endocrinopathy with anti-cytotoxic T lymphocyte antigen (CTLA-4) treatment (up to 15-20%) while the prevalence is extremely lower (<1%) with anti-PD-1 and anti-PD-L1 therapy." (PMID 32267349, 2020). "Although the different types of ICPI have been associated with both thyroid disorders and hypophysitis, the first is generally correlated with anti-PD1/anti-PDL-1 and the second to anti-CTLA-4." (PMID 33228219, 2020). "The descriptions of PD1 and PDL1 inhibitor-induced hypophysitis are more recent, probably because these drugs have been approved more recently than the approval of CTLA4 inhibitor." (PMID 33066179, 2020). "Prior studies on the comparison of endocrine toxicity spectrum between anti-CLTA-4 and anti-PD-1 showed that hypophysitis is closely related to anti-CTLA-4 monotherapy, and thyroid dysfunction is closely related to anti-PD-1 monotherapy." (PMID 32507965, 2020). "(a) Anti-CTLA-4 monotherapy was more related to hypophysitis (or resulting in hypopituitarism) and adrenal insufficiency." (PMID 32507965, 2020). "In their review, hypophysitis was more common with anti-CTLA-4 agents, whereas thyroid dysfunction was more frequent with anti-PD-1 agents." (PMID 33014837, 2020). "Hypophysitis is more frequent in patients receiving anti-CTLA-4 (up to 0–17%), especially in males around 60 years-old and 2–3 months after beginning ICPI." (PMID 33228219, 2020). "The most common endocrinopathies reported from clinical trials include hypothyroidism and hypophysitis in patients treated with anti-PD-1/PD-L1 antibodies and anti-CTLA4, respectively." (PMID 33425733, 2020). "Hypophysitis is less common with anti-programmed cell death protein-1 (PD-1) and anti-programmed death ligand 1 (PD-L1) mAbs than anti-CTLA-4 mAbs." (PMID 31511065, 2019).